MTOR (mechanistic target of rapamycin kinase)
Diseases named in the same sentence as MTOR in open-access papers (continued):
Sharing a sentence is not in itself a finding about the gene and the disease.
cancer (continued). "The Akt/mTOR signaling cascade is a classic driver pathway in human cancers." (PMID 39227365, 2024). "Furthermore, NVP-BEZ235 targets the mammalian target of rapamycin (mTOR) results decreasing the expression levels of phosphorylated Akt, inducing cancer cell death invitro and inhibiting cancer cell proliferation in vivo." (PMID 39003454, 2024). "Considering the central role of the PI3K/Akt/mTOR pathway in the growth, proliferation, and other functions of cancer cells, this may be a potential mechanism by which mTOR inhibitors suppress tumorigenesis after transplantation." (PMID 39224537, 2024). "Moreover, the cancer cells treated with nelfinavir showed reduced mTOR activity and increased ATF4-mediated SESN2 expression level." (PMID 37284849, 2023). "Studies have shown that more than 70% of cancer patients have excessive activation of mTOR." (PMID 37601696, 2023). "ROS are known to hyperactivate PI3K/Akt/mTOR (Phosphoinositide 3-Kinases/Protein kinase B/mammalian Target Of Rapamycin), an intracellular pathway playing an important role in cell cycle regulation, specifically proliferation, cancer, and longevity." (PMID 37597078, 2023). "Alternatively, metformin may preferentially target cancer cells with aberrant mTOR activation induced by the CXCL12/CXCR4-mediated pathway." (PMID 37760498, 2023). "Though there is no direct evidence to elucidate the mechanism for m6A-regulated amino acid metabolism, a series of vital signature pathways such as mTOR have been reported to be tightly controlled by m6A, thus providing a novel avenue for cancer therapy by targeting a m6A-amino acid axis." (PMID 37015927, 2023). "The activation of mTOR-AKT signaling mediates the progression of NDRG1-related cancer." (PMID 37858101, 2023). "The PI3K/AKT/mTOR signaling pathway, which controls multiple cellular processes including metabolism, motility, proliferation, growth, and survival, is one of the most frequently dysregulated pathways in human cancers." (PMID 38033496, 2023). "Multiple mTOR inhibitors have received approval for the treatment of human cancers." (PMID 37513916, 2023). "Further studies are needed to analyze whether LAT1 targeting against the tumor microenvironment affects cancer-related molecules other than mTOR in patients with CRC during chemotherapy." (PMID 36768934, 2023). "Furthermore, GO and KEGG enrichment analyses suggested that AARS2 was closely links with cell cycle, mTOR signaling pathway, and cancer metabolism activity." (PMID 37990642, 2023). "An early diagnosis, for example, of KS, in which the mainstay of treatment is based on the minimization of the immunosuppression and treatment with an mTOR inhibitor, could be fundamental to treating cancer but also avoid graft rejection." (PMID 36691019, 2023). "Previously, we have shown that Uro A, a natural gut microbial metabolite which is also involved in enhancement of gut barrier integrity can downregulate the oncogenic PI3K/AKT/mTOR signaling pathway, induce cell-cycle arrest, and increase apoptosis in cancer cells." (PMID 37448553, 2023). "Research evidence suggests that ETS1 may accelerate the development of cancer by influencing the function of the PI3K/AKT/mTOR signaling pathway." (PMID 37046729, 2023). "A study found that PI3K/AKT/mTOR pathway resulted in the overexpression of immunorelated genes (PD‐L1, CSF1, and CSF1R) or cytotoxic T lymphocyte‐associated protein 4 (CTLA4) in microglia or cancer cells in the microenvironment of brain metastases." (PMID 35822637, 2023). "While this activity has yet to be definitively demonstrated in humans, the conservation of the localization signal in human GARS1 implies that mTOR activation through GARS1 could be an advantageous pathway exploited by cancer cells." (PMID 38235113, 2023).
cancer (continued). "Moreover, treating cancer cells with cholesterol-lowering drugs including simvastatin significantly attenuated cell cancer cell proliferation via suppression of the PI3K/mTOR pathway." (PMID 37754524, 2023). "Therefore, the inhibition of mTOR is an important drug target in cancer chemotherapy, and if possible, rapamycin is incorporated into the treatment regimen." (PMID 37443747, 2023). "The phosphatidylinositol 3-kinase (PI3K)/V-AKT murine thymoma viral oncogene homolog (AKT)/mammalian target of rapamycin (mTOR) signaling cascade is also a well-studied signaling pathway that controls normal cells and cancer cells growth, proliferation, and survival." (PMID 38239196, 2023). "It is possible to effectively analyze the PI3K/AKT/mTOR signaling pathway as an appropriate treatment option because it is connected with several elements of cell growth and survival and is commonly activated in many different types of cancer." (PMID 36597032, 2023). "Activation of the PI3K/AKT/mTOR pathway has been demonstrated in multiple KRAS-positive cancers." (PMID 37154160, 2023). "The mTOR pathway is the second most altered signaling cascade in cancer." (PMID 36650715, 2023). "Furthermore, activation of the AKT/mTOR pathway is known to play a profound role in cancer progression, and GSK-3β itself is involved in this pathway." (PMID 37754254, 2023). "Inhibition of mTOR activity is an effective approach to cancer therapy." (PMID 36594084, 2023). "However, in cancer, abnormally activated mTOR/PI3K-Akt signaling stimulates tumor cells to grow, metastasize, and become resistant to treatment." (PMID 36902107, 2023). "Considering known cancer-relevant signaling pathways, the greatest overlap of these genes was observed for the adherence junction pathway (6% of candidate genes) followed by hedgehog (4.1%) and mTOR (3.9%) signaling." (PMID 36624125, 2023). "The mTOR signaling pathway has been shown to be deregulated in many cancers." (PMID 36671489, 2023). "Given the critical roles of mTOR signaling in maintaining cellular homeostasis, it could affect cancer cell behavior in multiple aspects, including metabolism, energy sensing, and protein synthesis." (PMID 37415733, 2023). "PI3K/AKT/mTOR is a major pathway in human cancer and is crucial in cell proliferation, metastasis, and metabolism, and blocking the related targets of this pathway can exert an inhibitory effect on cancer." (PMID 37834269, 2023). "Several miRNAs modulate ferroptosis in cancer cells with the involvement of mTOR, 4EBP1, and HIF1A." (PMID 36835100, 2023). "The inhibition of the mTOR signaling axis downregulates the malignant phenotype of cancer cells." (PMID 36768924, 2023). "Applications of proteasome or mTOR inhibitors such as rapamycin derivatives to enhance cancer cell autophagy could therefore be a promising treatment strategy for ESCC with PSMD2 overexpression." (PMID 36998052, 2023). "The obtained findings may confirm the anticancer effect of rapamycin in the form of decreased cell proliferation and justify the use of mTOR inhibitors in the treatment of cancer patients." (PMID 37658979, 2023). "Therefore, the PI3K/Akt/mTOR pathway has been considered one of the most attractive targets for cancer treatment." (PMID 36979714, 2023). "The signalling pathways underlying IL11 effects in cancer were mostly thought JAK/STAT3 related but, based on more recent data, MEK/ERK and — in particular — LKB1/AMPK/mTOR signalling, may now feature." (PMID 38054591, 2023). "Moreover, several researchers have previously reported that high expression of LAT1 in several resected cancer samples, including CRC, is associated not only with mTOR activation, but also with cancer metastasis, recurrence, and poor prognosis." (PMID 36768934, 2023). "Moreover, it was observed that PD-L1 expression on cancer cells also drives Akt/mTOR signaling, thus boosting tumor glycolysis with the subsequent depletion of environmental glucose and a restriction of T-cell functions." (PMID 37895302, 2023).
cancer (continued). "Metformin can also reduce cancer cell proliferation by inhibiting mTOR protein synthesis." (PMID 37737550, 2023). "mTOR is conserved from yeast to human and senses coordinately diverse signals such as nutrients, oxygen, hormones, and stress, being deregulated in multiple age-related diseases including cancer." (PMID 37110415, 2023). "Furthermore, it has been shown that genetic variations in mTOR complex components are closely related to cancer." (PMID 36851259, 2023). "Indeed, it has been shown that targeting PI3K/AKT/mTOR-mediated autophagy is a double-edged sword in cancer." (PMID 36982677, 2023). "This suggested that MYC amplification-driven resistance to mTOR-targeted therapies may also occur in human cancer patients." (PMID 37642941, 2023). "Furthermore, PIM kinases interact with the PI3K/AKT/mTOR pathway to drive cancer cell proliferation and survival." (PMID 37943821, 2023). "CNI-free immunosuppression after LTx based on mTOR inhibitors were presented as a conference abstract and included 12 long term patients (three with malignancy) converted to a CNI-free everolimus-based immunosuppressive regimen mainly to preserve kidney function." (PMID 37200246, 2023). "In addition, regarding Raptor as a scaffold for mTOR activity is an over-simplification, it was reported that mTORC1-independent Raptor also makes sense in cell metabolism and cancer progression." (PMID 37304865, 2023). "This was expected to obtain potent PI3K/mTOR dual inhibitors among them and summarize the structure–activity relationship in order to lay a foundation for further research in the field of treatment of malignant tumors." (PMID 36986560, 2023). "Studies showed that the upregulation of mTOR signaling may promote growth factor receptor signaling, angiogenesis, glycolytic activity, lipid metabolism, cancer cell migration, and the suppression of autophagy, leading to tumor growth and progression." (PMID 36701037, 2023). "KEGG enrichment analysis revealed that differentially expressed genes in risk categories were mostly engaged in neutrophil extracellular trap formation, transcriptional misregulation in cancer, mammalian target of rapamycin (mTOR) signaling pathway, proteoglycans in cancer." (PMID 37946148, 2023). "Hyperactivation of the PI3K/AKT/mTOR signaling pathway has previously been reported to be central to the control of cell viability, apoptosis, cell cycle, metabolism, and chemoresistance in multiple human cancers, including USC." (PMID 36773034, 2023). "On the other hand, oncogenes may be activated by class I PI3K, AKT, and mTOR, contributing to the inhibition of autophagy and the promotion of cancer." (PMID 36814212, 2023). "It has been reported that the constitutive phosphorylation of Akt in cancer cells activates different targets for tumor development as a pathway to chemoresistance in cancer, and the PI3K/Akt/mTOR pathway inhibition has been associated with high survival rates in different types of cancer." (PMID 37687058, 2023). "Likewise, rapamycin (a mTOR inhibitor, also known as Sirelimus) is used to treat certain malignant tumors, and Akt inhibitors (such as MK2206) are undergoing clinical trials for cancer therapy." (PMID 36761736, 2023). "During TC progression and due to cancer genomic instability across more dedifferentiated TC histologies, the prevalence of mutations in genes linked to SWI/SNF chromatin remodeling complex and the PI3K/AKT/mTOR, MAPK, and JAK/STAT pathways increased." (PMID 38139812, 2023). "The PI3K/AKT/mTOR pathway is commonly dysregulated in cancer." (PMID 37909334, 2023). "Moreover, PI3K/AKT/mTOR inhibitors, when combined with other therapies, have demonstrated effectiveness against ARID1A‐deficient cancers." (PMID 38041544, 2023).
cancer (continued). "As multiple genes of the PI3K/Akt/mTOR signaling pathway are frequently found mutated in cancer and interact with other crucial genes in oncogenesis, such as PTEN, they arguably constitute important therapeutic targets in the cancer therapeutic field." (PMID 37762410, 2023). "The mTOR (Target of Rapamycin) pathway is involved in both cancer and aging." (PMID 37057884, 2023). "Numerous studies have shown a complex crosstalk between the mTOR kinase signaling pathway and YAP, suggesting that YAP and mTOR proteins, by regulating each other, may contribute to cancer progression." (PMID 37048121, 2023). "Determining the mechanism underlying the interplay between the mTOR signalling pathway and DNA methylation may help us to better estimate the therapeutic effect of mTOR inhibitors in cancers, including HCC." (PMID 37088830, 2023). "Our results suggest that the reduced cell viability induced by ALA and observed in both cancer cell lines, could occur via mTOR-mediated inhibition of autophagy." (PMID 38069431, 2023). "As such, targeting mTOR signaling may be a feasible approach to attenuate the aberrant energy metabolism of cancer cells and improve cancer therapy." (PMID 37190313, 2023). "Therefore, cancer treatment strategies that inhibit mTOR have attracted much attention and achieved clinical successes." (PMID 36768934, 2023). "Conversely, MSI2 is a crucial regulator of cancer stem cell programs by acting on the stability and translation of target mRNAs that encode key proteins of oncogenic signaling pathways (e.g., TGFβR1/SMAD3, NUMB/Notch, PTEN/mTOR, MET, and MYC)." (PMID 37107676, 2023). "The serine/threonine protein kinase mTOR occurs in many human cancers." (PMID 37511932, 2023). "The PI3K/AKT/mTOR pathway plays a vital role in controlling cell survival, metabolism, cell and tumor growth, and protein synthesis in various conditions, including normal physiological processes and pathological states, with a particular emphasis on cancer." (PMID 37601653, 2023). "Crosstalk between the mTOR pathway and ER stress is involved in cancer drug resistance." (PMID 38223508, 2023). "Mouse studies have shown that mTOR inhibitors such as Rapamycin, which formerly received FDA approval for cancer treatments, successfully rescued deficiencies in social and repetitive behaviors in postnatal day 7 TSC-mutant mice, and only social deficits in 6-week-old TSC-mutant mice." (PMID 36792602, 2023). "mTOR forms two multiprotein complexes, mTORC1 and mTORC2, that are targetable from cancer drugs." (PMID 36672617, 2023). "Notably, it has been reported that the mTOR signaling pathway was frequently activated in human cancer." (PMID 37781030, 2023). "The mTOR pathway is involved in estrogen signal transduction in the endometrium and its dysregulation plays a critical role in the development and pathogenesis of endometrial diseases including cancer." (PMID 37176048, 2023). "In addition, the activity of mTOR is also frequently deregulated in many kinds of human cancers, such as breast, lung, liver, prostate, renal and pancreatic cancers." (PMID 37049920, 2023). "In an attempt to understand the molecular mechanisms underlying the interaction between PD-L1 and EMT in the malignant neoplasms studied, the following signaling pathways were analyzed in the present systematic review: ERK/STAT, Rho GTPase, PI3K/AKT, AKT/mTOR, and TGF-β." (PMID 37026608, 2023). "All these results confirmed that NUAK1 impacts cancer cell survival, indicating that its inhibition, either alone or combined with other drugs that block Akt or mTOR activity, could be a therapeutic strategy in cancers with hyperactivated Akt signaling." (PMID 38135881, 2023). "FIR-preconditioned normal cells might promote a cellular self-defense system to evade transformed cancer cells via MITF-Akt-mTOR-exosome trajectory." (PMID 37123908, 2023). "Akt/mTOR pathway has multiple initiation mechanisms, and it manifests in some cancer subtypes." (PMID 36849137, 2023).
cancer (continued). "The mammalian target of rapamycin (mTOR), also known as the mechanistic target of rapamycin, is a central regulator of cancer cell metabolism and plays a pivotal role in coordinating various cellular processes related to growth, proliferation, and energy utilization." (PMID 38002335, 2023). "For this reason, mTOR inhibition has raised significant interest in clinical cancer research." (PMID 36765661, 2023). "If the tolerability can be improved, perhaps dual PI3K/mTOR inhibitors could be beneficial for cancer therapy because studies have shown PI3K to be involved in chemotherapy resistance." (PMID 38983593, 2023). "In addition, CR and fasting reduces fibroblast collagen deposition in the TME and cancer fibrosis by inhibiting, respectively, mTOR and TGF-β signaling, which promotes the conversion of fibroblast in cancer associated fibroblast (CAF)." (PMID 37568713, 2023). "Differential metabolites between Ns and Ir-NPs group were significantly enriched in propanoate metabolism, protein digestion and absorption, central carbon metabolism in cancer, aminoacyl-tRNA biosynthesis, mTOR signaling pathway, nicotinate and nicotinamide metabolism, and phenylalanine metabolism." (PMID 36891263, 2023). "Furthermore, the phosphatidyl-inositol 3-kinase/mammalian target of the rapamycin (PI3K/AKT/mTOR) pathway is involved in survival, cell growth, cancer progression, tumour radio- and chemoresistance, as well as invasion and migration." (PMID 36639527, 2023). "One of the specific roles of PI3K/mTOR pathways in PCa is their involvement in the regulation of autophagy, a homeostatic process involved in several cell activities, including tissue growth, differentiation, metabolic modulation, and cancer development." (PMID 36769263, 2023). "Also, this study reveals that the compound prunetrin can potentially inhibit cancer growth by activating the caspase cascade and inhibiting the Akt/mTOR pathways." (PMID 37571343, 2023). "In addition, glutamine can also activate mammalian target of rapamycin (mTOR) and maintain reactive oxygen species (ROS) homeostasis of cancer cells." (PMID 37127605, 2023). "Accordingly, targeting eIF4E-eIF4A-dependent translation downstream of mTOR enhances the activity of rapamycin and this may be an effective therapeutic strategy to target oncogenic translation programs in cancer." (PMID 36900235, 2023). "Thus, our study has implications for the development of more effective treatment strategies for patients with cancer through targeting the mTOR pathway in antigen-specific CD8+ T cells." (PMID 36378537, 2023). "Increased mTOR signaling promotes cancer cell proliferation, as well as survival." (PMID 37838167, 2023). "Thus, research on mTOR modulation involves various compounds to interfere with the metabolic processes in cancer cells." (PMID 38057772, 2023). "Hence, the mTOR signaling pathway is also targeted in anticancer research, where a combination of mTOR inhibitors with drugs have proven to be effective in cancer therapy." (PMID 36831355, 2023). "mTOR, PI3K, protein kinase B (Akt), MAPK/ERK, Wnt, Notch, and hedgehog signaling pathways are associated with the regulation of cell proliferation, differentiation, survival, apoptosis, invasion, migration, angiogenesis, and metastatic spread of cancer cells." (PMID 37132286, 2023). "In conclusion, it is inferred that the mTOR signalling pathway may contribute to cancer development by blocking autophagy and apoptotic pathways." (PMID 37513916, 2023). "PI3Ks, AKT and mTOR are involved in the survival signaling of cancer cells." (PMID 38188676, 2023). "As mTOR inhibitors in monotherapy have been shown to be effective in several types of cancer, numerous clinical trials have explored the potential of mTOR inhibitors in combination with other molecularly-targeted or chemotherapeutic agents to reverse drug resistance." (PMID 37968262, 2023).